C4BPA (complement component 4 binding protein alpha)
Description:
Controls the classical pathway of complement activation. It binds as a cofactor to C3b/C4b inactivator (C3bINA), which then hydrolyzes the complement fragment C4b. It also accelerates the degradation of the C4bC2a complex (C3 convertase) by dissociating the complement fragment C2a. Alpha chain binds C4b. It also interacts with anticoagulant protein S and with serum amyloid P component.
Synonyms: C4bp; PRP
Tractability: Antibody: its Gene Ontology location is reachable by antibodies, with high confidence; UniProt places it where antibodies can reach, with medium confidence; UniProt predicts a signal peptide or a membrane-spanning region. PROTAC: its protein half-life has been measured.
Gene: Protein-coding gene on chromosome 1 (207,102,319 to 207,145,047, forward strand). Ensembl gene ENSG00000123838.
Subcellular location: Secreted
Pathways (Reactome):
Disease: Dengue virus activates/modulates innate and adaptive immune responses
Immune System: Regulation of Complement cascade
Gene Ontology:
Molecular function: protein binding; RNA binding
Biological process: negative regulation of complement activation, classical pathway; positive regulation of protein catabolic process; regulation of opsonization; response to symbiotic bacterium; T cell mediated immunity; regulation of immune response; response to other organism
Cellular component: blood microparticle; extracellular region; plasma membrane
Genetic constraint (gnomAD): Loss-of-function variants: 21 observed, 42.19 expected, observed/expected ratio (o/e) 0.5, 90% interval 0.35 to 0.72. The upper end of that interval is the gene's LOEUF score, 0.72, which puts it in group 2 of 6, group 1 being the genes least tolerant of losing a copy. Missense variants: 485 observed, 627.5 expected, observed/expected ratio (o/e) 0.77, 90% interval 0.72 to 0.83. Synonymous variants: 213 observed, 226.55 expected, observed/expected ratio (o/e) 0.94, 90% interval 0.84 to 1.05.
Homologues: Orthologues: chimpanzee C4BPA (97% identical), rabbit C4BPA (62% identical), rat C4bpa (59% identical), guinea pig C4BPA (53% identical), mouse C4bp (41% identical), pig C4BPA (18% identical). Paralogues in human: CR2 (30% identical), CSMD3 (28% identical), CR1 (27% identical), CSMD2 (27% identical), CSMD1 (26% identical), SVEP1 (24% identical), CR1L (18% identical), SELP (18% identical), SEZ6L (17% identical), CFH (17% identical), SEZ6 (17% identical), SEZ6L2 (17% identical), and 27 more.
Diseases named in the same sentence as C4BPA in open-access papers:
C4BPA is named in the same sentence as 63 diseases in open-access papers, as found by Europe PMC text mining. Sharing a sentence is not in itself a finding about the gene and the disease. The quoted sentences say what the papers report.
COVID-19 (6 papers, 2021 to 2024). A disease caused by infection with severe acute respiratory syndrome coronavirus 2. "Genes induced in BA.1 patients, such as C4BPA, have also been reported to be regulated in COVID-19 patients." (PMID 35441161, 2022). "LGALS3BP abundance in COVID-19 patients closely correlated with proteins and regulators of the complement cascade (C6, C9, C4BPA, and C4BPB)." (PMID 34099652, 2021). "Other proteins that could potentially be employed in therapies against COVID-19 but that so far have not been associated with the disease are CD5L, VDBP, A1BG, C4BPA, PGLYRP2, SERPINC1, and APOH." (PMID 37371071, 2023). "In addition, other proteins that could be employed in therapies against COVID-19 but that so far have not been associated with the disease are CD5L, VDBP, A1BG, C4BPA, PGLYRP2, SERPINC1, and APOH." (PMID 37371071, 2023). "C-reactive protein (CRP), alpha-1-acid glycoproteins (A1AG1 and A1AG2), and CXCL7 were all found to be considerably higher in critically ill patients than in non-critical COVID-19 patients, whereas CCD34, C4BPA, and GELS were found to be significantly lower." (PMID 38291452, 2024). "Concentrations of select chemokines (CXCL8, CXCL10, CCL2, CCL3, CCR1) and complement factors (C2, C9, CFD, C4BPA, C5AR1, CR1) were examined at mRNA and protein levels with regard to a COVID-19 course (ICU vs. non-ICU group) and CMV status at different time intervals." (PMID 36232655, 2022).
breast carcinoma (4 papers, 2019 to 2025). "In addition, C4BPA has been detected in tissue and blood samples taken from patients with breast cancer." (PMID 40757647, 2025). "C4BPA had been identified as a novel serum biomarker for pancreatic ductal adenocarcinoma (PDAC) and breast cancer." (PMID 36177001, 2022). "Furthermore, we found that a group of variants on chromosome 1 (rs1202980, rs60220284, and rs45574833) located in the C4BPA, LOC107985251, and TRIM46 genes are related to breast cancer." (PMID 36859360, 2023).
lung carcinoma (4 papers, 2013 to 2024). "For lung cancer, we ensure that C4BPA, SESN3, and IRS1 are highly expressed in some specific groups." (PMID 33133130, 2020). "On the other hand, lower levels of the C1QB, C3 and C4BPA proteins have been detected in lung cancer tissues than in normal lung tissues." (PMID 30841875, 2019). "Microarray-based transcriptome profiles revealed lower levels of the C1QB, C3 and C4BPA mRNAs in lung cancer tissues than in healthy tissues." (PMID 30841875, 2019). "On one hand, higher levels of the complement proteins C1QB, C3 and C4BPA were detected in plasma from patients with lung cancer than in healthy subjects." (PMID 30841875, 2019). "For lung cancer, we select five essential genes, such as PYGB, C4BPA, SESN3, MMP10, IRS1." (PMID 33133130, 2020). "However, seven genes selected from FSL (FOXA2, C4BPA, SCGB3A1, DDX58, CCNDBP, TMSB4X, and CXCL17), and one gene selected from both FSL as well as RSL (CD9), were up-regulated in the lung cancer tissues, but not significantly (P > 0.05)." (PMID 23374247, 2013).
biliary tract cancer (3 papers, 2019 to 2024). "Several candidate protein molecules, including C4b-binding protein alpha chain (C4BPA), help in distinguishing chronic pancreatitis from PDAC and biliary tract cancers." (PMID 30863442, 2019).
colorectal cancer (2 papers, 2016 to 2021). A primary or metastatic malignant neoplasm that affects the colon or rectum. "The other study through HCT116 colorectal cancer cell immunoprecipitation validated the association between C4BPA and NF-κB pathway-related genes, which showed that C4BPA played a significant role in the regulation of NF-κB dependent apoptosis." (PMID 35173767, 2021).
endometriosis (2 papers, 2011 to 2024). The growth of functional endometrial tissue in anatomic sites outside the uterine body. "Abnormally decreased levels of C4BPA were found in the mid-secretory endometria of women with implantation failure and endometriosis." (PMID 39272751, 2024). "Indeed, C4BPA transcript levels are abnormally decreased in the endometrium during the receptive phase in women with endometriosis, implantation failure and unexplained recurrent abortion, suggesting it may have a role in embryo implantation." (PMID 21272326, 2011).
mastitis (2 papers, 2021 to 2024). Inflammation of breast tissue during lactation or postpartum due to an obstructed duct or infection. "Our results provide the primary basis for understanding the role of C4BPA in mastitis and fat metabolism, which enables the researchers to follow the innovative direction of investigating genes associated with fat metabolism and mastitis." (PMID 35173767, 2021). "Therefore, in this study, we thoroughly explored the mechanism of the C4BPA gene in milk fat metabolism and mastitis in bMECs." (PMID 35173767, 2021). "C4BPA is a candidate gene for anti-mastitis and high-fat milk." (PMID 35173767, 2021). "Overall, the results of this study showed that the C4BPA gene through TLR4/NF-κB played a significant role in regulating the expression of all the major genes of immunity and inflammation factors associated with mastitis in dairy cattle." (PMID 35173767, 2021). "Therefore, we speculated that C4BPA could regulate TG levels when mastitis occurs." (PMID 38397050, 2024). "Due to the significant binding ability of C4BPA with CD40, the C4BPA is a key factor involved in dairy cattle mastitis." (PMID 35173767, 2021).
Obesity (2 papers, 2019 to 2025). Accumulation of substantial excess body fat. "We observed a significant decrease in C4BPA protein expression in the CRPS group, which shows the potential benefit of CRPS in inflammatory responses in people with obesity." (PMID 30736312, 2019).
ovarian carcinoma (2 papers, 2022 to 2024). A malignant neoplasm originating from the surface ovarian epithelium. "CADM1 overexpression potentially inhibits the migration and invasion of ovarian cancer cells by regulating the upstream regulatory factor C4b-binding protein (C4BPA) and the PI3/Akt/mTOR signaling pathway." (PMID 38481252, 2024). "Regulation of C4BPA can inhibit the PI3K/Akt/mTOR signaling pathway induced by the overexpression of CADM1, thereby affecting the migration and invasion of ovarian cancer cells." (PMID 36177001, 2022).
pancreatic ductal adenocarcinoma (2 papers, 2021 to 2022). An infiltrating adenocarcinoma that arises from the epithelial cells of the pancreas. "We have previously identified C4b-binding protein α-chain (C4BPA) as a serum biomarker for the early detection of pancreatic ductal adenocarcinoma (PDAC)." (PMID 34167573, 2021).
psychotic disorder (2 papers, 2021). An abnormal condition of the mind that involves a loss of contact with reality. "Decreased C4b-binding protein alpha chain (C4BPA) and C4b-binding protein beta chain (C4BPB) levels were found in children preceding the onset of psychotic disorder." (PMID 33670154, 2021).
schizophrenia (2 papers, 2015 to 2017). A major psychotic disorder characterized by abnormalities in the perception or expression of reality. "We have examined the association of schizophrenia with the gene encoding C4-binding protein (C4BPB/C4BPA), a potent circulating soluble inhibitor of the classical and lectin pathways of complement." (PMID 26305563, 2015). "However, our results did not support the involvement of C4BPB/C4BPA in schizophrenia." (PMID 26305563, 2015).
thrombosis (2 papers, 2020 to 2022). "These genes included STIM1 and C4BPA, which impact platelet reactivity and/or thrombosis risk, as well as MASTL and TPM4, which influence megakaryo-thrombopoiesis." (PMID 32600345, 2020). "C4BPA was also found to be a risk factor for venous thrombosis via an unknown protein S-independent mechanism." (PMID 35935235, 2022).
atherosclerosis (1 paper, 2025). A disease characterized by the build-up of fatty material and calcium deposition in the arterial wall resulting in partial or complete occlusion of the arterial lumen. "In addition, C4BPA can affect the activity of the complement system, which may influence the pathogenesis and development of atherosclerosis by modulating the activity of the complement system and the inflammatory response." (PMID 40950552, 2025).
Cirrhosis (1 paper, 2016). A chronic disorder of the liver in which liver tissue becomes scarred and is partially replaced by regenerative nodules and fibrotic tissue resulting in loss of liver function. "The PPI network in HCC has no seed, but in cirrhosis C4BPA is introduced as seed protein." (PMID 28224023, 2016).
escherichia coli infection (1 paper, 2017). Infection with the organism Escherichia Coli. "Furthermore, gene expression analysis facilitates the identification of host factors contributing to disease susceptibility, such as C4BPA expression in enterotoxigenic Escherichia coli infection." (PMID 29326715, 2017).
glioblastoma (1 paper, 2025). The most malignant astrocytic tumor (WHO grade IV). "Many of the identified differentially expressed genes are understudied in glioblastoma; however, several are key regulators of tissue remodeling (MFAP4 and ALX4), mesoderm development (TBX5 and ALX4), and immune modulation (FUT2, C4BPA, MFAP4, and GRM4)." (PMID 41066027, 2025).
hepatocellular carcinoma (1 paper, 2024). A malignant tumor that arises from hepatocytes. "In EVs derived from blood plasma, a correlation between C4BPA, modulation of the tumor microenvironment, and immune escape through the complement system has been suggested in patients with hepatocellular carcinoma, showing a higher abundance of C4BPA compared to control patients." (PMID 39057100, 2024).
inflammatory bowel disease (1 paper, 2024). A spectrum of small and large bowel inflammatory diseases of unknown etiology. "C4BPA expression was found to be increased in patients with irritable bowel syndrome, while C4BPB expression was found to be increased in patients with inflammatory bowel disease." (PMID 38671889, 2024).
liver disease (1 paper, 2024). "For instance, some of the complement proteins identified in this study, including C1QBP, C4BPA, CLU, and SERPING1, have also been identified in proteomic analyses as potential biomarkers in metabolic dysfunction-associated steatotic liver disease/metabolic dysfunction-associated steatohepatitis." (PMID 38573776, 2024).
lymph node metastasis (1 paper, 2021). "Additionally, according to Cox proportional hazard models, lymph node metastasis and low stromal C4BPA expression were independent factors in poor prognosis of patients with PDAC via multivariate analysis." (PMID 34167573, 2021).
melanoma (1 paper, 2024). A malignant, usually aggressive tumor composed of atypical, neoplastic melanocytes. "In EVs, human studies have already identified C4BPA in serum EVs from patients with melanoma." (PMID 39057100, 2024).
myeloma (1 paper, 2022). "Conversely, myeloma patients presented a significant and consistent upregulation of C4BPA, a regulator of complement activation that accelerates the decay of the classical pathway." (PMID 35800053, 2022). "We report a set of PB EV-proteins (PDIA3, C4BPA, BTN1A1, and TNFSF13) with a new biomarker potential for myeloma patient outcomes." (PMID 35800053, 2022).
non-small cell lung carcinoma (1 paper, 2022). A group of at least three distinct histological types of lung cancer, including non-small cell squamous cell carcinoma, adenocarcinoma, and large cell carcinoma. "C4BPA, as a cofactor of soluble complement inhibitor factor I, can help non-small cell lung cancer cells escape the cytotoxic activity of the complement system and enhance the invasiveness of tumor cells." (PMID 36712848, 2022).
pancreatic tumors (1 paper, 2023). "In pancreatic tumors, a comprehensive proteomic study identified the C4b-binding protein α-chain (C4BPA) as a novel serum biomarker, showing promise for early stage PDAC detection and differentiation from other gastroenterological cancers." (PMID 37628784, 2023).
pneumonia (1 paper, 2021). An acute, acute and chronic, or chronic inflammation focally or diffusely affecting the lung parenchyma, caused by an infection in one or both of the lungs (by bacteria, viruses, fungi, or mycoplasma.). "Among genes upregulated in ACE2-expressing AT2 cells, we identified genes that are highly pertinent to lung epithelial biology and disease such as HHIP (lung branching and COPD), FGG (fibrosis, pneumonia, and inflammation), and C4BPA (complement system, pneumonia, and infection)." (PMID 33809063, 2021).
preeclampsia (1 paper, 2025). Preeclampsia is a hypertensive disorder of pregnancy that is characterized by new-onset hypertension with proteinuria presenting after 20 weeks of gestation, and depending on mild or severe forms may initially present with severe headache, visual disturbances, and hyperreflexia. "Notably, proteins linked to hematological and immune pathways were highlighted: C4b-binding protein alpha chain (C4BPA) and complement factor H (CFH), both acting as activators of complement pathways, with elevated levels observed in pregnancy-related conditions, such as preeclampsia." (PMID 40430124, 2025).
Sepsis (1 paper, 2021). Sepsis is defined as life-threatening organ dysfunction caused by a dysregulated host response to infection. "The most modulated genes were Granzyme B, Complement Factor B, Complement Component 4 Binding Protein Alpha, IL-12, and SERPINB-1 that were closely related to sepsis-induced immunological process." (PMID 33868226, 2021).
spontaneous abortion (1 paper, 2020). Expulsion of the product of FERTILIZATION before completing the term of GESTATION and without deliberate interference. "Additionally, the mRNA levels of complement component 4-binding protein alpha (C4BPA), a key inhibitor of the complement system, were increased during the implantation window in women, but decreased in women which suffered repeated implantation failure and unexplained recurrent spontaneous abortion." (PMID 32766237, 2020).
steatosis (1 paper, 2021). Increased lipid within the cytoplasm of cells. "A Wilcoxon test on C9 and C4BPA genes revealed gene downregulation within the steatosis samples." (PMID 34829865, 2021).
type 1 diabetes (1 paper, 2016). "There were two significant interactions of SNPs with HLA genotype on type 1 diabetes; rs2230199 in C3 (p = 0.0125) and rs4844573 in C4BPA (p = 0.0275)." (PMID 27306948, 2016). "When type 1 diabetes was the outcome, in DR3/4 subjects, there was nominal significance for two SNPs: rs17615 in CD21 [HR 1.52; 95% CI 1.05–2.20; p = 0.025] and rs4844573 in C4BPA [HR 0.63; 95% CI 0.43–0.92; p = 0.017]." (PMID 27306948, 2016).
venous thromboembolism (1 paper, 2022). Occlusion of the lumen of a vein by a thrombus that has migrated from a distal site via the blood stream. "In addition, C4BPA was reported as a risk gene of venous thromboembolism with expression quantitative trait loci effects." (PMID 36319843, 2022).